METTL3 (methyltransferase 3, N6-adenosine-methyltransferase complex catalytic subunit)
Diseases named in the same sentence as METTL3 in open-access papers (continued):
Sharing a sentence is not in itself a finding about the gene and the disease.
non-small cell lung carcinoma (continued). "In non-small cell lung cancer, METTL3 can recruit YTHDF1/3 and eIF3b to form translation initiation complex, thus promoting the translation of YAP." (PMID 35022030, 2022). "m6A methyltransferase METTL3 mediated autophagy increases the sensitivity of non-small cell lung cancer cells to gefitinib by β-elemene." (PMID 34124065, 2021). "For example, METTL3 regulated cisplatin resistance of non-small cell lung cancer via activation of YAP or cell autophagy." (PMID 34514103, 2021). "It has also been reported that miR-33a can inhibit the proliferation of non-small cell lung cancer (NSCLC) cells by targeting M6A regulatory factor METTL3 mRNA 3'UTR binding site." (PMID 33428597, 2021). "METTL3 mediates lncRNA RP11–138 J23.1 (RP11) or MALAT1-miR-1914-3p-Yes associated protein (YAP) axis to enhance the migration and invasion of CRC and non-small cell lung cancer (NSCLC)." (PMID 32767982, 2020). "In this study, we found that m6A methyltransferase METTL3-mediated autophagy played an important role in reversing gefitinib resistance by β-elemene in non-small cell lung cancer (NSCLC) cells." (PMID 33177491, 2020). "In human non-small cell lung carcinoma, METTL3, which undergoes sumoylation, has a reduced ability to catalyze m6A, resulting in enhanced tumorigenesis." (PMID 31801551, 2019). "To illustrate, in non-small cell lung cancer, METTL3-mediated m6A modification could enhance the stability of methylated lncRNA-RMRP transcripts, which further promotes TGFBR1 transcription and the activation of TGFBR1/SMAD2/SMAD3 signaling pathway." (PMID 40089501, 2025). "As demonstrated in the extant literature, METTL3 in CAFs-derived exosomes has been shown to promote proliferation, invasion, and glutamine metabolism in non-small cell lung cancer (NSCLC) cells by inducing m6A modification of SLC7A5 and stabilising its expression." (PMID 40598593, 2025). "Similarly, CAFs secrete VEGFA to elevate METTL3 expression levels in non-small cell lung cancer cells, which subsequently facilitates m6A methylation of ras-related C3 botulinum toxin substrate 3 (RAC3) mRNA." (PMID 40986143, 2025). "For example, studies have demonstrated that circRNA exosomal membrane protein 1 of EVs in patient serum samples can serve as a novel biomarker for non-small cell lung cancer, and it promotes non-small cell lung cancer proliferation by regulating the miR-524-5p-METTL3/SOX2 axis." (PMID 40696664, 2025). "In non-small cell lung cancer, METTL3 may promote the development of the disease by facilitating the maturation of pri-miR-21-5p, upregulating miR-21-5p, and targeting the inhibition of FDX1." (PMID 40276654, 2025). "SUMOylation of METTL3 is important for promoting the growth of non-small cell lung cancer (NSCLC)." (PMID 40097750, 2025). "Furthermore, studies have demonstrated that demonstrated that METTL3 overexpression increased vimentin expression in human non-small cell lung cancer cells." (PMID 41345738, 2025). "Another study shows that miR-33a inhibits proliferation and promotes differentiation of non-small cell lung cancer cells (NSCLCs) by binding to the 3′UTR of METTL3, which suggests that METTL3 may be a novel therapeutic target for NSCLC." (PMID 39457524, 2024). "Similarly, the down regulation of miR-524-5p also up-regulates the expression of METTL3 in non-small cell lung cancer cells." (PMID 36614216, 2023). "MALAT1 was increased in non-small cell lung cancer due to METTL3-mediated high m6A modification." (PMID 37986103, 2023). "METTL3 promoted yes-associated protein (YAP) mRNA translation through YTHDF1/3 and eIF3B, and increased the stability of YAP mRNA by regulating the MALAT1/miR-1914-3p/YAP axis to induce non-small cell lung cancer (NSCLC) treatment metastasis and resistance b." (PMID 35711459, 2022). "Besides, SUMOylation of METTL3 is of importance for the promotion of tumor growth at lysine residues K177, K211, K212 and K215 in non-small cell lung carcinoma (NSCLC)." (PMID 31142332, 2019).
non-small cell lung carcinoma (continued). "Interestingly, METTL3 within CAFs orchestrates IL-18 expression through m6A-mediated mRNA modification, thereby triggering NF-κB signaling to modulate PD-L1-dependent immunosuppression in non-small cell lung cancer." (PMID 40986143, 2025). "SUMOylation of METTL3 by SUMO1 promotes tumorigenesis in human non-small cell lung carcinoma (NSCLC)." (PMID 37391814, 2023). "METTL3 relies on YTHDF1/3 and eIF3B to promote yes-associated protein (YAP) mRNA translation and increases YAP mRNA stability by modulating the MALAT1–miR-1914-3p–YAP axis, thereby inducing treatment resistance and metastasis in non-small cell lung cancer (NSCLC)." (PMID 32398132, 2020). "In non-small cell lung cancer (NSCLC), METTL3 enhances the stability of the lncRNA DLGAP1 antisense RNA 2 (DLGAP1-AS2), which interacts with YTHDF1 and promotes c-MYC mRNA stability via m6A modification." (PMID 41373022, 2025). "For example, in non-small cell lung cancer (NSCLC), METTL3 acts as a catalyst for ferroptosis by targeting GPX4 and SLC7A11." (PMID 40271153, 2025). "In non-small cell lung cancer (NSCLC), METTL3 directly promotes YAP translation and increases YAP activity by regulating the MALAT1-miR-1914-3p-YAP axis, leading to drug resistance and metastasis." (PMID 38627760, 2024). "In non-small cell lung cancer (NSCLC), METTL3 is expressed at higher levels than in paired normal tissues and is involved in gefitinib resistance." (PMID 38576024, 2024). "In Non-Small Cell Lung Carcinoma(NSCLC), METTL3-mediated m6A modification destabilizes PD-L1 mRNA, resulting in a reduction of PD-L1 expression." (PMID 39372415, 2024). "In non-small cell lung cancer, lncRNA ABHD11-AS1 is more stable after being modified with m6A mediated by METTL3, and promotes aerobic glycolysis of NSCLC through ABHD11‐AS1/EZH2/KLF4 axis." (PMID 37582735, 2023). "For example, in non-small cell lung carcinoma (NSCLC) cells, exosomal miR-4443 targets METTL3 expression and negatively regulates METTL3-mediated m6A modifications on FSP1 and ferroptosis." (PMID 37497000, 2023). "In non-small cell lung cancer (NSCLC), miR-4443 inhibits the protein expression of methyltransferase-like 3 (METTL3), which is responsible for N6-methyladenosine (m6A) methylation, leading to upregulation of FSP1 expression and regulation of ferroptosis." (PMID 37371948, 2023). "METTL3 induces the expression of genes such as ATG5 and ATG7 in gefitinib-resistant non-small cell lung cancer and regulates autophagy to promote drug resistance in tumor cells." (PMID 37996892, 2023). "For example, in non-small-cell lung cancer, MeRIP-Seq discovers that there was a m6A modification site in ABHD11-AS1 and METTL3 promotes the ABHD11-AS1 transcript stability to increase its expression." (PMID 35501316, 2022). "A higher level of m6A mRNA methylation initiated by METTL3 facilitates YAP mRNA translation leading to an acceleration of the invasive and metastatic activities of non-small cell lung cancer cells." (PMID 33882457, 2021). "In non-small cell lung carcinoma (NSCLC), METTL3 promotes the expression of FSP1, which enhances FSP1-mediated ferroptosis induced by cisplatin treatment." (PMID 34315512, 2021). "In non-small-cell lung cancer (NSCLC), the METTL3-YTHDF3-MALAT1-miR-1914-3p-YAP signaling axis plays a crucial role in the invasion and metastasis of tumor." (PMID 33292652, 2020). "In keeping with these findings, miR-33a targeting of the METTL3 3′ UTR leads to the downregulation of METTL3 expression and suppression of non-small cell lung cancer (NSCLC) proliferation." (PMID 32911345, 2020). "Additionally, the methyltransferase METTL3 induced m6A modification of lncRNA NEAT1 to stabilize NEAT1 expression, thereby accelerating tumorigenesis in non-small cell lung cancer." (PMID 38351022, 2024).
non-small cell lung carcinoma (continued). "Additionally, the MALAT1-miR-1914-3p-YAP axis is regulated by METTL3-initiated m6A mRNA methylation, which enhances YAP activity and directly stimulates YAP translation in non-small cell lung cancer (NSCLC)." (PMID 38125749, 2023). "Combination effect of METTL3 with YTHDF3 can improve the stability of MALAT1 and increase the expression of MALAT1, thus increase the stability of YAP mRNA by regulating MALAT1-miR-1914-3p-YAP axis in non-small cell lung cancer." (PMID 35022030, 2022). "METTL3 promoted YAP translation by recruiting YTHDF1/3 and eIF3b, and increased YAP expression by the MALAT1/miR-1914-3p axis, leading to drug resistance and metastasis in non-small-cell lung carcinoma (NSCLC)." (PMID 35164788, 2022). "And METTL3 also directly promotes YAP translation and increases YAP activity by regulating the MALAT1-miR-1914-3p-YAP axis to induce drug resistance and metastasis of non-small cell lung cancer." (PMID 34124065, 2021). "Moreover, METTL3 increased the expression of circIGF2BP3 through m6A modification, and further enhanced the expression of PD-L1 through the miR-328-3p/miR-3173-5p/PKP3/OTUB1 pathway, ultimately leading to immune escape in non-small cell lung cancer." (PMID 38632251, 2024). "First, CAFs can raise m6A activity inside tumor cells without necessarily transferring RNA: in non-small cell lung cancer (NSCLC), CAF-conditioned cues (notably VEGFA) induce tumor-intrinsic METTL3, elevating m6A on RAC3 and driving AKT/NF-κB signaling, invasion, and in vivo growth." (PMID 41280938, 2025).
cervical cancer (82 papers, 2017 to 2026). A primary or metastatic malignant neoplasm involving the cervix. "For example, METTL3, an m6A writer, is significantly associated with LN metastasis and a poor prognosis in cervical cancer." (PMID 37914704, 2023). "Another study found that METTL3 was highly increased in cervical cancer tissue and cells, which was linked to lymph node metastases and a poor prognosis in cervical cancer patients." (PMID 36091006, 2022). "In this study, we investigated the clinical significance of iASPP and METTL3 expression and association between the two proteins in cervical cancer." (PMID 32201509, 2020). "Furthermore, the involvement of the miR-30c-5p targeting the METTL3/KRAS axis is crucial in driving the progression of cervical cancer, shedding light on the molecular mechanisms underlying cervical cancer growth and metastasis." (PMID 39155349, 2024). "Thus, we postulated that the METTL3/DLG2/Hippo signaling pathway was implicated in the progression of cervical cancer, and this hypothesis has been substantiated in the current work." (PMID 39856747, 2025). "In cervical cancer, it was found that METTL3 increased the metabolism of glutamine in cervical cancer cells through m6A methylation of SLC38A1 mRNA157." (PMID 41522342, 2026). "A previous study revealed that aspartyl-tRNA synthetase 1 antisense 1 (DARS-AS1) recruited METTL3 to mediate its m6A modification in cervical cancer progression." (PMID 39856747, 2025). "In our previous study, TBP was shown to be responsible for the upregulation of METTL3 in cervical cancer cells." (PMID 39800682, 2025). "Further, METTL3 expression at mRNA and protein levels was higher in clinical cervical cancer tissues and cells than in normal cervical tissues and cells." (PMID 39856747, 2025). "This study elucidates the specific regulatory role of METTL3 in the progression of cervical cancer, thereby enriching our understanding of the mechanisms underlying the development of this malignancy." (PMID 39856747, 2025). "Together, all these results implied the crucial function of the METTL3/HDAC6 axis in the pathogenesis of cervical cancer." (PMID 39535388, 2025). "Together, these results indicated that HDAC6 plays a role in the METTL3‐regulated malignancy of cervical cancer in vitro." (PMID 39535388, 2025). "For instance, METTL3 accelerates cervical cancer progression by promoting m6A modification of the lncRNA FOXD2-AS1 and enhancing the stability of FOXD2-AS1." (PMID 39904996, 2025). "Subsequent data from the IHC assay showed that METTL3 expression was higher in cervical cancer tissues when compared with normal cervical cancer tissues." (PMID 39856747, 2025). "METTL3 mediates HSPA9 m6A modification to promote the malignant development of cervical cancer (CC)." (PMID 41256854, 2025). "For example, in cervical cancer, we identified three different mechanisms of METTL3 that can promote the progression of cervical cancer." (PMID 41256854, 2025). "In particular, the combination of METTL3 inhibitors or DLG2 activators with current cervical cancer therapies has the potential to improve treatment outcomes by leveraging a more comprehensive and targeted approach against the disease." (PMID 39856747, 2025). "Meanwhile, studies have demonstrated that miR-30c-5p promotes iron death of cervical cancer cells by inhibiting the METTL3/KRAS axis, consequently inhibiting tumor growth, migration, and metastasis." (PMID 39155349, 2024). "In cervical cancer, miR-30c-5p targets the METTL3/KRAS axis, fostering ferroptosis and concomitantly suppressing tumor growth and metastasis." (PMID 39551792, 2024). "In contrast, METTL3 boosts cervical cancer cell proliferation by enhancing HK2 stability via YTHDF1 recruitment." (PMID 39219199, 2024). "The modification of its coding region by METTL3 can enhance its translational efficiency, thereby facilitating glycolysis in cervical cancer and promoting the progression of the disease." (PMID 38343637, 2024).
cervical cancer (continued). "In cervical cancer, METTL3 plays an important role in the different biological processes of cervical cancer by regulating the transcription and translation levels of different oncogenic targets." (PMID 38343637, 2024). "In vitro and in vivo, METTL3 overexpression significantly promotes the metastasis of cervical cancer cells." (PMID 39289775, 2024). "METTL3 expression in cervical cancer leads to accelerated cell cycle progression and tumor proliferation." (PMID 39033180, 2024). "For cervical cancer, METTL3/FOXD2-AS1 accelerates the cervical cancer progression via an m6A-dependent modality." (PMID 38351139, 2024). "For example, METTL3 has been found to stimulate MDSCs differentiation in cervical cancer, and the expression of the two is positively correlated, promoting tumor progression and affecting prognosis." (PMID 39033180, 2024). "DARS-AS1/DARS can regulate the expression of ATG5 via m6A modification mediated by METTL3/14, indicating the development of autophagy in cervical cancer cells." (PMID 39468015, 2024). "In cervical cancer, METTL3 induces m6A modified NR4A1 RNA degradation through the YTHDF2-DDX6 pathway to manipulate tumor metastasis." (PMID 37996892, 2023). "Pathological tissue analysis of cervical cancer likewise showed that METTL3 expression positively correlates with the level of CD33+ MDSCs." (PMID 37996892, 2023). "In cervical cancer patients, the levels of METTL3 and CD33+ MDSCs in tumor tissues are significantly associated with reduced DFS or OS." (PMID 36008936, 2022). "The level of METTL3 is positively correlated with CD33+MDSCs in cervical cancer (CC) patients, and both METTL3 and CD33+MDSCs are independent prognostic factors for CC." (PMID 36439186, 2022). "Only one study found that METTL3 downregulated the expression of RAGE in cervical cancer cells, inhibited cell viability, increased cell apoptosis, and enhanced the sensitivity of these cells to cisplatin therapy." (PMID 35945641, 2022). "PD-L1 expression increased dramatically in cervical cancer tissues and was significantly linked to ALKBH5, FTO, METTL3, RBM15B, YTHDF1, YTHDF3, and ZC3H13 expression levels." (PMID 36091006, 2022). "We found that METTL3, a core m6A methyltransferase component, is upregulated and functions as an oncogene in cervical cancer." (PMID 36566195, 2022). "IHC results showed that METTL3 was significantly downregulated in cervical cancer specimens, whereas the METTL3 protein was mainly localized in the cytoplasm of normal adjacent cervix." (PMID 34514103, 2021). "Herein, we reported that METTL3 inhibited viability and induced apoptosis of cervical cancer cells and increased the cisplatin sensitivity via downregulating RAGE." (PMID 34514103, 2021). "A Cell Counting Kit-8 (CCK-8) assay was performed to measure the viability of cervical cancer cells after METTL3 modulation." (PMID 34514103, 2021). "Our immunohistochemistry (IHC) data showed that METTL3 was highly expressed in para-cancerous compared with cervical cancer tissues." (PMID 34514103, 2021). "Meanwhile, quercetin enhanced the chemosensitivity of cervical cancer cells by downregulating the expression of P-gp and methyltransferase-like 3 (METTL3), which mediated HeLa cell proliferation and apoptosis." (PMID 34680171, 2021). "One study revealed that elevated expression of METTL3 is correlated with poor prognosis of cervical cancer patients." (PMID 34514103, 2021). "Our previous study revealed that quercetin potentiated the chemosensitivity to cisplatin in cervical cancer cells, along with the downregulation of METTL3 expression." (PMID 34514103, 2021). "In this study, the expression of METTL3 was first discovered to be downregulated in both cervical cancer tissues and cell lines by IHC and western blotting analyses, respectively." (PMID 34514103, 2021). "Among the five cervical cancer cell lines, SiHa and C33A cells displayed the highest expression levels of METTL3." (PMID 34514103, 2021).